EREG (epiregulin)
Diseases named in the same sentence as EREG in open-access papers (continued):
Sharing a sentence is not in itself a finding about the gene and the disease.
breast cancer (continued). "Based on these studies, we propose that EREG contributes to the formation of pre-invasive lesions in a subset of breast cancers." (PMID 26215578, 2015). "In the control donors and in the majority of breast cancer patients, EREG plasma levels remained low." (PMID 23597096, 2013). "As Massagué and co-workers have shown in a mouse xenograft model, HBEGF sustains the specific dissemination of human mammary tumor cells to the brain, whereas dissemination to the lung is accompanied by EREG expression." (PMID 23597096, 2013). "Human recombinant EREG promotes cell proliferation in pancreatic and bladder cancer in a dose-dependent manner, whereas an EREG knockdown inhibits tumor growth in hepatocellular carcinoma, breast cancer, head and neck squamous cell carcinoma (HNSCC), cervical cancer, glioma, and multiple myeloma." (PMID 38398101, 2024). "Moreover, EREG is upregulated in the metastatic lung tumors of breast cancer and bladder cancer in murine models of lung metastasis." (PMID 38398101, 2024). "The oncogenic role of long intergenic non-protein coding RNA 885 (LINC00885) is correlated with early breast cancer progression; which may promote cell proliferation and survival through EREG/EGFR and FOXM1 pathways." (PMID 34884633, 2021). "Similar to EREG, drugs that interfere with AREG, particularly in chemoresistant breast cancers, effectively acquiesce tumor growth, tumor-associated macrophage (TAM) infiltration and block the activation of diverse EGF receptors (ErbB1, 3 and 4+ ErbB2 HER2/Neu)." (PMID 34299315, 2021). "The EGFR pathway activated by EREG and the PI3K/Akt/mTOR pathway activated by FGF10 are well known to be part of the mechanisms of resistance to HER2-targeted therapy in HER2-positive breast cancer." (PMID 35954313, 2022). "In one study using normal human epidermal keratinocytes, 2 nM EREG induced ERK phosphorylation more strongly than 10 nM EGF, whereas in another study using MCF-7 mammary cancer cells, 10 μM EREG and 16 nM EGF induced ERK phosphorylation to a similar level." (PMID 34667080, 2022). "A set of lung metastasis signature (LMS) genes, including EREG, COX2, and MMP1/2, was identified in breast cancer cells with lung metastasis potential." (PMID 34884633, 2021). "Since p130Cas is induced by anti-estrogen therapy and doxorubicin in breast cancer cells, the effects of standard CRC chemotherapy on p130Cas/BCAR1 and EREG expression were investigated in CRC cell lines and metastasis tissues samples." (PMID 34830244, 2021). "Together, these studies lead to identification of a novel pathway involving EREG and MMP-1 that contributes to the formation of early stage breast cancer." (PMID 26215578, 2015). "Notably, in breast cancer, SDC1 expression was negatively correlated with the scores for RNAss and positively correlated with EREG." (PMID 41364407, 2025). "TGFβ stimulated genes matrix metallopeptidase 2 (MMP2), epiregulin (EREG), and vascular endothelial growth factor A (VEGFA) were also critical regulators of lung metastasis of breast cancer and correlated with the prognosis of breast cancer." (PMID 38245723, 2024). "EREG can induce the Warburg effect through EGFR signaling activation, which increases the expression of glycolytic genes, including GLUT3, HK2, and PDK1, in breast cancer cells resistant to tamoxifen." (PMID 34884633, 2021). "Furthermore, EREG and MMP-1 overexpression increase tumor cell survival in early-stage breast cancer." (PMID 34884633, 2021). "In cell culture, breast cancer cells with secondary resistance to trastuzumab displayed an up-regulation of mRNA expression for EGF, TGFα, HB-EGF and heregulin, while the expression of AREG mRNA was downregulated and the expression of epiregulin and betacellulin mRNA was unchanged." (PMID 27933395, 2017).
breast cancer (continued). "Analysis of EREG and MMP-1 expression in the TCGA database did not reveal a significant association, possibly due to the fact that these samples represent invasive breast cancers, rather than early stage breast cancers." (PMID 26215578, 2015). "Elevated EREG plasma protein levels, however, were detected in a minor fraction of our breast cancer patient data set, suggesting that EREG is not a primary contributor to breast cancer progression mediated by monocytes in humans." (PMID 23597096, 2013).
lung cancer (21 papers, 2016 to 2026). A malignant neoplasm involving the lung. "Using human and mouse lung epithelial cell lines, we observed that recombinant (r)EREG induced wound healing and increased cell growth at levels similar to EGF, thus supporting EREG as a marker of this hallmark for early-stage lung cancer." (PMID 39771097, 2024). "EREG has been identified as a chemoresistance-associated gene based on RNA-seq data analysis of patients with lung cancer and NSCLC cell lines." (PMID 38398101, 2024). "Cigarette smoking is a well-known risk factor for lung cancer, and carcinogens in cigarette smoke induce EREG upregulation in bronchial epithelial cells." (PMID 38398101, 2024). "Studies have shown that the expression of EREG was associated with various tumor diseases such as lung cancer, gastric cancer and colon cancer, which revealed that EREG played an important role in the occurrence and development of tumors." (PMID 32906628, 2020). "Lastly, epiregulin, a known growth factor upregulated in premalignant stages of lung cancer specifically during tumor-promoting inflammation, was also significantly elevated above control in response to 5 μg/mL WSP." (PMID 41938737, 2026). "Targeting the EGF-family ligand EREG using antibody-drug conjugates or neutralizing antibodies offers tumor specificity, as EREG is highly expressed in colorectal and lung cancers with low expression in normal tissues." (PMID 41175573, 2025). "Consistently, treatment with ERK inhibitors blocks EREG‐dependent tumor-promoting effects in colorectal and lung cancer models, validating downstream ERK as an effector of EREG signaling." (PMID 41175573, 2025). "The role of EREG on cancer development has been demonstrated in various cancers such as breast cancer, lung cancer, and colorectal cancer." (PMID 38673992, 2024). "The current understanding of the roles of EREG in lung tumorigenesis and therapeutic resistance accentuates the therapeutic potential of targeting the EREG/EGFR pathway in lung cancer." (PMID 38398101, 2024). "One is epiregulin (EREG), a ligand for the EGFR receptor; EGFR is a known pathway important to lung cancer development and involved in the proliferative hallmark of cancer." (PMID 39771097, 2024). "EREG is usually overexpressed in several human cancers including bladder, brain, breast, colorectal and lung cancer and it is used as a predictive biomarker i.e. in metastatic colorectal cancer." (PMID 36994208, 2023). "EREG expression was reported to be associated with metastasis and shorter survival time in NSCLC, which was in agreement with our study, where lung cancer patients with high EREG mRNA level had a shorter survival time." (PMID 35551652, 2022). "Depletion of MUC1 deficiency in fibroblasts and epithelial cells led to increased EREG expression that promoted lung cancer development through the EGFR/AKT pathway." (PMID 34884633, 2021). "This likely reflects autocrine EGFR stimulation, as supported by increased expression of EGF ligands such as epiregulin (EREG) in lung cancer cells." (PMID 30890751, 2019). "In human lung cancer, EREG and AREG mRNA or protein levels are elevated in a subset of NSCLC cell lines as well as NSCLC specimens and predict poor survival." (PMID 30412601, 2018). "Importantly, several studies have investigated human anti-EREG antibody development for treating diseases such as colon cancer and, in the future, potentially as an intervention for lung cancer." (PMID 39771097, 2024). "Interestingly, it has been reported that increased EREG expression by Mucin-1 (MUC1) deficiency in fibroblasts and epithelial cells accelerated lung cancer development through the EGFR/AKT pathway." (PMID 38673992, 2024). "It is concluded that enriched EREG/ErbB signaling is activated and could be a potential target for resistant lung cancer." (PMID 35551652, 2022).
lung cancer (continued). "Consistently, the overall survival time and disease-free survival time of EREGhigh population were shorter than EREGlow population, which indicated highly expression of EREG promoted the progression of lung cancer and implied that EREG was correlated with resistance." (PMID 35551652, 2022). "EREG is usually overexpressed in various cancers, including glioma and lung cancer; however, whether the expression of EREG plays a critical role in distinct types of cancers with CSC properties that confer tumor metastasis and drug resistance remains unclear." (PMID 34884633, 2021). "It would be interesting if these EGFR ligands such as TGF-alpha, amphiregulin or epiregulin, might serve as biomarker in head and neck or lung cancer patients as we found for EGF." (PMID 34115785, 2021). "Thus, it is possible that ADAM17 contributes to EREG-induced therapeutic resistance in lung cancer." (PMID 38398101, 2024). "Of note, AREG, EREG, FOSL1, MYC, and PLAU are involved in the EGFR signaling pathway, which is a key pathway in lung cancer development." (PMID 39858622, 2025). "First, we compared the mRNA levels of common EGFR ligands in lung cancer (HB-EGF, EGF, TGF-α, BTC, AREG, and EREG) by using the gene expression dataset GSE30219, GSE3141, and GSE50081." (PMID 36439487, 2022). "Our results demonstrating that EREG in HNSCC can mimic EGFR mutations by sustaining activation of the EGFR-Erk pathway raised the question of whether EREG could be used to identify the patient group most responsive to EGFR-targeted therapies, similar to EGFR-activating mutations in lung cancer." (PMID 32929368, 2020). "Our results led to identification of a novel pathway involving EREG and MMP-1, which contributes to the growth and progression of lung cancer." (PMID 27995036, 2016).
colon cancer (16 papers, 2009 to 2025). "Previous research has demonstrated that colon tumors are more frequently associated with microsatellite instability, overexpression of epiregulin, chromosomal instability, and epidermal growth factor receptor amplification compared to rectal tumors." (PMID 38978992, 2024). "In colon cancers with liver metastasis, EREG was identified as a metastasis-associated gene through gene expression analysis." (PMID 34884633, 2021). "Similar up-regulated epiregulin expression has also been linked to activation of the Kras signalling pathway in colon cancer." (PMID 32398031, 2020). "EREG has also been identified as a liver metastasis-associated gene in colon cancer." (PMID 38398101, 2024). "For example, left-half colon cancer has high expression of epiregulin (EREG) and amphiregulin (AREG) proteins, while right-half colon cancer has high mutation rates of the TGFbR2 and BRAF genes." (PMID 41182556, 2025). "In a colon cancer xenograft model, EREG was expressed in both LGR5 (an intestinal stem cell marker)-positive and drug-resistant LGR5-negative cells, thereby indicating the involvement of EREG in cancer stemness." (PMID 38398101, 2024). "In support of this possibility there is work showing a role for stromal myofibroblast production of amphiregulin and epiregulin in promoting colon tumor growth in the setting of inflamed human colon." (PMID 23805328, 2013). "The strongest evidence for a role of epiregulin during tumorigenesis was obtained in Ki-ras-mediated signaling of colon cancer cells." (PMID 19529782, 2009). "Additionally, our study found that the expression of ASRGL1 and EREG can influence the sensitivity of colon cancer to certain antitumor drugs, and the specific mechanisms underlying these effects warrant further exploration." (PMID 39883700, 2025). "In a metastatic murine model of colon cancer, treatment with an anti-EREG antibody induced antitumor activity against tumors derived from EREG-expressing LGR5-positive cells, thereby suggesting that targeting EREG is effective in defeating cancer stemness and chemoresistance." (PMID 38398101, 2024). "Furthermore, subsequent inhibition of EREG had reversed the resistance of cancer cells in colon cancer." (PMID 35551652, 2022). "Importantly, EREG was correlated to the characteristics of cancer stem cells in esophageal cancer and colon cancer." (PMID 35551652, 2022). "This speculation was supported by findings from another study that showed colon cancer resistance to the 5-FU drug due to upregulation of EREG." (PMID 35551652, 2022). "Furthermore, treatment with the anti-EREG antibody significantly suppressed colon cancer cell adhesion and spread." (PMID 34884633, 2021). "This anti-EREG antibody blocks the stimulation of EGFR signaling by EREG and not by EGF, and it inhibits the cell adhesion of EREG-expressing human colon cancer cells." (PMID 38398101, 2024). "EREG protein expression levels were both detected in LGR5-positive and drug-resistant LGR5-negative colon cancer cells." (PMID 34884633, 2021). "Analysis of primary colon cancer tissues showed the existence of both epiregulin+ LGR5+ and epiregulin+ LGR5− colon cancer stem cells: both these cell populations displayed a tumor-initiating capacity." (PMID 29652830, 2018). "Interestingly, epiregulin was expressed at the level of both LGR5+ and LGR5− colon cancer stem cells." (PMID 29652830, 2018). "In patient P0009, a quadruple negative colon cancer case, both epiregulin and amphiregulin exhibited extraordinary over-expression based on RNA-Seq data analysis, making a case for cetuximab treatment." (PMID 27245685, 2016).
glioblastoma (11 papers, 2013 to 2024). The most malignant astrocytic tumor (WHO grade IV). "The study also identified epiregulin (EREG) as a core oncogene in glioblastoma that affects immunity by influencing PD-L1 expression." (PMID 37665670, 2023). "Individual cases presenting EREG upregulation were also observed by using PCR approaches in both anaplastic astrocytoma and glioblastoma, as compared to normal brain tissues." (PMID 24330607, 2013). "Furthermore, Epiregulin was shown to enhance tumorigenicity by activating the ERK/MAPK pathway in a mouse model of glioblastoma." (PMID 38514807, 2024). "Even though EREG has not been reported previously in the context of ASD, a study showed that overexpression of EREG in the brain could lead to a brain tumor, and it was involved in tumor exacerbation in a glioblastoma cell line." (PMID 37108604, 2023). "Moreover, increased EREG protein expression in patients with glioblastoma was highly correlated with a higher tumor grade and poor OS." (PMID 34884633, 2021). "EREG is highly expressed in glioblastoma and can activate ERK singling to promote tumorigenesis." (PMID 34884633, 2021). "We also examined EREG status in several glioblastoma cell lines and in malignant glioma." (PMID 24330607, 2013). "The Rab27b-EREG pathway may improve the efficacy of radiotherapy for glioblastoma multiforme (GBM)." (PMID 34884633, 2021). "Since EREG contributes to the angiogenesis process as well as to tumor metastasis in breast carcinoma models, we further considered its possible relationship to IRE1α and to glioma development and analyzed its status in several glioblastoma cell lines and in malignant glioma." (PMID 24330607, 2013). "Previous studies of the EGF family members amphiregulin (AR) and epiregulin (EPR) have mainly focused on their roles in cell proliferation and tumorigenesis within the mammary gland, ovary, and other organs as well as glioblastoma." (PMID 25675253, 2015). "While EREG expression is not per se increased in glioblastoma, EREG expression is higher in high-grade compared to low-grade glioma, and loss of EREG correlates with increased survival, supporting a potential role of EPIREGULIN in cell proliferation." (PMID 38514807, 2024). "EREG is the core onco-immunological biomarker of CuAS and modulates the cross-talk between VEGF and CD99 signaling in glioblastoma, and CuAS may provide support for immunotherapy and chemotherapy." (PMID 36647156, 2023).
gastric cancer (10 papers, 2017 to 2025). A primary or metastatic malignant neoplasm involving the stomach. "In gastric cancer, it was found that the EREG mRNA expression was an independent predictor of poor survival, and that the overall survival was significantly reduced in patients with gastric cancer with high expression." (PMID 37035196, 2023). "Furthermore, the JNK signaling pathway activated by EREG affects the ERK/p38 signaling pathway, which may be associated with the progression of gastric cancer in certain cases." (PMID 39795027, 2025). "Among these cytokines, Notch‐3, galectin‐8, EphA1, epiregulin, and FGF‐12 have been reported to be upregulated in gastric cancer." (PMID 30873760, 2019). "The human colonic adenocarcinoma cell line DLD1 and the human gastric cancer cell line AGS were selected as high and low EREG-expressing cancer cell lines, respectively." (PMID 28333127, 2017).